TP63 (tumor protein p63)
Diseases named in the same sentence as TP63 in open-access papers (continued):
Sharing a sentence is not in itself a finding about the gene and the disease.
asthma (4 papers, 2018 to 2025). "We identified initial evidence of asthma-associated Super-Enhancers encompassing genes encoding transcription factors (TP63) and enzymes regulating lipid metabolism (PTGS1)." (PMID 33362848, 2020). "Here the authors find that genetic loci shared between asthma and chronic rhinosinusitis highlight Jak-STAT signaling, and link a Finnish-enriched TP63 variant with nasal polyps." (PMID 41213931, 2025). "We focused on Epithelium-dominant TFs and found those encompassed by BEC-SEs have been previously implicated in lung development (FOXA1) and asthma, nasal polyposis, and mucociliary development (TP63, TP73)." (PMID 33362848, 2020). "Fine-mapping singled a low frequency (AF = 1.39 %) TP63 variant rs190865056-A that significantly increases risk for CRSwNP (OR = 1.52 [95 % CI 1.331–1.734]), with no significant impact on asthma." (PMID 41213931, 2025). "CRSwNP-specific heritability, carried in part by rare disease-specific variants such as the TP63 missense variant rs190865056-A, seems to differ from shared heritability, at least in its lack of impact on allergic phenotypes, while asthma-specific heritability shows few differing comorbidities." (PMID 41213931, 2025). "We found that a number of TFs were encompassed by BEC-SEs including TP63, a well-defined marker of basal cells, and TP73, a key player in mucociliary development and observed enrichment for FOXI1 sites in asthma DERs, a TF shown to characterize the recently identified ionocytes." (PMID 33362848, 2020).
colon cancer (4 papers, 2017 to 2022). "Pancreatic ductal adenocarcinoma and colon cancer patients with high levels of TP63 and Ago2 had a significantly lower overall survival time." (PMID 35459267, 2022).
colorectal cancer (4 papers, 2017 to 2022). A primary or metastatic malignant neoplasm that affects the colon or rectum.
COVID-19 (4 papers, 2021 to 2024). A disease caused by infection with severe acute respiratory syndrome coronavirus 2. "All of the 6 intersected genes have been reported to associate with COVID-19, including FGFR3, TP63, CXCL2, CCL20, IL1B and CXCL8." (PMID 37497545, 2023). "Interleukin 1 receptor-associated kinase 2 (IRAK2), upregulated in both COVID-19 and ICM, was associated with the upregulation of the FCER1 and TP63 pathways, both of which are associated with inflammation and immune activation (Figure A2A)." (PMID 34071557, 2021). "For example, ciliated and TP63/MUC5AC networks were enriched in some COVID-19 lungs, which are consistent with histopathologic IPF features that exhibit infiltration of fibrotic alveoli with airway basal cells and “honeycombing cysts” lined by mucus producing ciliated epithelia." (PMID 35857635, 2022). "The SOX2−/TP63+ Wnt-activated transcriptional signature of KRT5−/KRT17+ basaloid cells in IPF and SOX2− signature of KRT5−/KRT17+ basaloid cells in post-COVID-19 fibrosis suggest that loss of SOX2 expression may explain the formation of these distinct dysplastic lesions in lung disease." (PMID 38182591, 2024).
head and neck cancer (4 papers, 2014 to 2022). A primary or metastatic malignant neoplasm affecting the head and neck.
oral cancer (4 papers, 2017 to 2025). "In oral cancer, TP63 CNV was significantly associated with smoking history, while the incidence of TP63 CNV gain was considerably increased among smokers." (PMID 34796198, 2021). "Rescuing TP63 expression in SCC25 cells showed similar results, further supporting the involvement of the HOXA10-AS/TP63 axis in oral cancer progression." (PMID 35858923, 2022). "TP63 acts as a master regulator in epithelia development and in the progression of various cancers, but its role in oral cancer pathogenesis remains unknown." (PMID 28423539, 2017). "This spatial change served as a strong evidence for the regulation of TP63 mRNA processing by lncRNA HOXA10-AS, and its connection to oral cancer malignancy." (PMID 35858923, 2022).
Rapp-Hodgkin syndrome (4 papers, 2022 to 2025). A form of ectodermal dysplasia characterized by the association of anhidrotic ectodermal dysplasia with cleft lip/palate. "For example, the Arg279His mutation in TP63 has been found in classic EEC families and also in patients diagnosed with Rapp-Hodgkin syndrome, which blurs the clinical distinction between those entities." (PMID 41141084, 2025). "However, this patient has minimal scoliosis and no major documented manifestation of Rapp-Hodgkin syndrome, suggesting a reduced expressivity of the TP63 variant." (PMID 35346302, 2022).
glioblastoma (3 papers, 2013 to 2025). The most malignant astrocytic tumor (WHO grade IV). "According to the literature, among the genes whose expressions change after treatment and have an LTR12C element at the TSS site, only IRGM, GBP2, GBP5, and TP63 are known to play a meaningful role in glioblastoma." (PMID 40498028, 2025). "Moreover, TP63, a target of hsa-miR-203, has also been reported to be regulated by miR-21 in glioblastoma." (PMID 24039884, 2013). "Since similar observations have also been made in several GBM cell models, we aimed to study the effect of epi-drugs on the regulation of protein-coding genes, focusing on the TP63 gene, whose expression can start from LTR12C promoters in glioblastoma cell lines." (PMID 40498028, 2025).
Insulin resistance (3 papers, 2020 to 2024). Increased resistance towards insulin, that is, diminished effectiveness of insulin in reducing blood glucose levels. "TP63-/- mice develop obesity and insulin resistance linked to increased fatty acid synthesis and decreased fatty acid oxidation." (PMID 32349335, 2020). "TP63 knockout mice showed insulin resistance, obesity, and glucose intolerance; TP63 prevented these symptoms by increasing fatty acid synthesis and reducing fatty acid oxidation through the SIRT1/AMPKα2/LKB1 pathway." (PMID 33906607, 2021). "In diabetic mice and renal cells exposed to high glucose, reduced IRS‐1 levels caused significant up‐regulation of tumor protein 63 (TP63), which demonstrated the potential of TP63 in regulating IRS‐1 and insulin resistance." (PMID 37927197, 2024).
nasal polyps (3 papers, 2020 to 2025). "To date, however, the role of TP63 in nasal polyps remains to be shown." (PMID 34439758, 2021).
osteosarcoma (3 papers, 2019 to 2023). A usually aggressive malignant bone-forming mesenchymal neoplasm, predominantly affecting adolescents and young adults. "Through experimental verification, it was found that the pyroptosis gene TP63 plays an important role in the regulation of osteosarcoma pyroptosis." (PMID 36389801, 2022).
Premature ovarian insufficiency (3 papers, 2021 to 2024). Amenorrhea due to loss of ovarian function before the age of 40. "Lately, there is increasing evidence that TP63 mutations are connected with female infertility, including isolated premature ovarian insufficiency (POI) and syndromic POI." (PMID 34445673, 2021). "TP63-related cases were reported recently with infertility as a component of the syndromic phenotypes or isolated premature ovarian insufficiency (POI)." (PMID 34445673, 2021).
T-cell lymphomas (3 papers, 2022 to 2025). "Rearrangements of TP63, including TP63 fusions, are frequently described in several types of T-cell lymphoma, where they operate oncogenically via the generation of a truncated factor." (PMID 36009586, 2022).
Burkitt lymphoma (2 papers, 2018 to 2023). A rare form of malignant mature B-cell non-Hodgkin lymphoma. "Concomitant knockdown of TCL1 and TP63 affected AKT phosphorylation status in the Burkitt lymphoma cell line Raji, an observation that fits well with the model we proposed in which TCL1 plays a central and crucial role in multiple signaling pathways." (PMID 30151355, 2018). "In Raji Burkitt lymphoma, TCL1A has been connected with TP63." (PMID 37791059, 2023).
cervical (2 papers, 2014 to 2025). "TP63 has also been implicated as a biomarker of cervical disease progression." (PMID 25531390, 2014). "The Gene Expression Omnibus (GEO) datasets, were utilized to assess the expression profiles of TP63 and YAP1 in the cervical SCC and ADC samples by using the GEO2R tool." (PMID 40603978, 2025).
cervical squamous cell carcinoma (2 papers, 2014 to 2024). A squamous cell carcinoma arising from the cervical epithelium. "Immunohistochemistry showed that SOX2 and TP63 proteins clearly delineated tumour cells in invasive squamous cervical cancer." (PMID 25531390, 2014). "SOX2, HCG and TP63 mRNAs were also shown to be upregulated in cervical samples with HR-HPV+ve high grade dyskaryosis and SOX2 and TP63 immunohistochemistry identified cancerous cells, in HR-HPV+ve biopsies, from women with cervical squamous cell carcinoma." (PMID 25531390, 2014).
cervical tumors (2 papers, 2005 to 2014). "Microarray analysis identified among the most prevalent alterations in cervical tumors and cell lines the amplification of the RBP1- RBP2 (Retinol binding protein 1 and 2, 58.8%) and Tp63 (52.9% of the samples) genes, located at 3q21-q22 and 3q27-q29, respectively." (PMID 16004614, 2005).
chronic lymphocytic leukemia (2 papers, 2020 to 2021). "Papakonstantinou found different levels of methylation of TP63 in different subtypes of chronic lymphocytic leukemia." (PMID 32955083, 2020).
colorectal adenocarcinoma (2 papers, 2022). The most common type of colorectal carcinoma. "For the two transcription genes highly expressed in CSCC, TP63 could be used as a poor prognostic marker of colorectal adenocarcinoma, however, the oncogene function of STAT1 in colorectal adenocarcinoma was controversial." (PMID 35194959, 2022). "Among the genes associated with mbesQTLs and known to be differently expressed in colorectal adenocarcinoma tissue according to The Cancer Genome Atlas database, USP14, LOXL2 (lysyl oxidase-like 2) and TP63 (tumor protein 63) link the microbiota composition with cancer development." (PMID 35794137, 2022).
endometrial cancer (2 papers, 2015 to 2021). Primary or metastatic malignant neoplasm involving the endometrium (mucous membrane that lines the endometrial cavity). "TP63+ squamous differentiation in invasive endometrial cancer was also recently reported in a subset of Fbxw7/Pten knockout mice." (PMID 34941867, 2021).
glaucoma (2 papers, 2020 to 2024). Increased pressure in the eyeball due to obstruction of the outflow of aqueous humor. "Another TP63 variant (p.R343W) affecting the same amino acid residue has been reported in a patient with glaucoma and decreased central corneal thickness as well as findings consistent with lacrimo–auriculo–dento–digital syndrome (MIM 149730)." (PMID 32224865, 2020). "Peters anomaly in our patient and decreased corneal thickness associated with glaucoma in the previously reported patient may suggest that the Arg343 residue of TP63 plays a role in corneal development." (PMID 32224865, 2020).
hydronephrosis (2 papers, 2024 to 2025). Collection of urine in the renal pelvis that results in dilatation of the renal pelvis and calyces. "The monozygotic female twins described here possess a novel de novo heterozygous, pathogenic variant in the TP63 gene and are concordant for cutaneous erosions, absence of hair, cleft palate, and hydronephrosis." (PMID 41143230, 2025).
Infertility (2 papers, 2021 to 2025). "In contrast to the TP63 gene, variants in genes involved in meiosis often cause infertility in both females and males." (PMID 41393291, 2025).
keloid (2 papers, 2022 to 2024). An irregularly shaped, elevated mark on the skin caused by deposits of excessive amounts of collagen during wound healing. "A fibroblast-related diagnostic model for keloid based on a six-gene signature (CCNB1, EGFR, E2F8, BTG1, TP63, and IGF1) was proposed, showing high predictive accuracy in keloid diagnosis." (PMID 39157347, 2024). "As a result, consistent with the signal landscape at NPTX2, the binding signal of BRCA1 at TP63 is lower in keloid DF than normal DF and the chromatin is denser at the corresponding region in keloid DF." (PMID 36015648, 2022). "•CCNB1, EGFR, E2F8, BTG1, TP63, and IGF1 were associated with keloids." (PMID 39157347, 2024). "The established model based on CCNB1, EGFR, E2F8, BTG1, TP63, and IGF1 showed good performance and may be useful for keloid diagnosis." (PMID 39157347, 2024). "In comparison to levels in control tissues, the expression levels of CCNB1, EGFR, BTG1, as well as TP63 were evidently lower in the keloid tissues (P < 0.05), while the expression levels of E2F8 as well as IGF1 were evidently higher in the keloid tissues (P < 0.05)." (PMID 39157347, 2024). "In the training dataset, the expression levels of CCNB1, EGFR, E2F8, BTG1, as well as TP63 were remarkedly lower in the keloid samples than in the control samples (P < 0.05); however, the expression of IGF1 was evidently enhanced in the keloid samples elative to the control samples (P < 0.05)." (PMID 39157347, 2024).
lymphopenia (2 papers, 2024). Reduction in the number of lymphocytes. "Here, we present a case of a female infant born with TP63-related syndrome and profound T cell lymphopenia, first uncovered through newborn screening." (PMID 39364398, 2024).
peripheral T-cell lymphoma (2 papers, 2022 to 2024). "Recent advancements in molecular diagnostics, such as testing for DUSP22 and TP63 rearrangements, could offer valuable insights into ALK-negative ALCL prognosis and aid in distinguishing it from peripheral T-cell lymphoma (PTCL) NOS." (PMID 39610919, 2024).
pterygium (2 papers, 2021 to 2025). A wedge-shaped fibrovascular lesion arising from the bulbar conjunctiva and extending to the cornea. "Our further analysis of pathways controlled by upstream regulator TP63 suggested increased EMT in pterygium, regulated by BMP2, BMP6, SNAI1 and KLF7." (PMID 34769520, 2021). "Signature genes for the two epithelial limbal progenitor cell types (cluster 10, cluster 9) that express TP63 were unchanged or downregulated in both pterygium and pinguecula." (PMID 34769520, 2021). "Our further analysis of pathways controlled by upstream regulator TP63 suggested increased activity of the Notch and Wnt epithelial differentiation pathways in pterygium, and identified WNT7B, WNT9A, PPM1N and HES5 as likely involved." (PMID 34769520, 2021). "Nevertheless, TP63 mRNA expression was decreased in corneal epithelial cells of both SND and pterygium subjects, referring to a slower turnover of these epithelial cells." (PMID 40094891, 2025). "Comparing pinguecula and pterygium, IPA predicted activation of pathways controlled by upstream regulators TP63, MYC and KLF4, transcription factors that control epithelial cell fate." (PMID 34769520, 2021). "In the comparison between pinguecula and pterygium subgroups, IPA predicted activation of pathways controlled by MYC, TP63 and KLF4 upstream regulators, which control epithelial cell fate." (PMID 34769520, 2021). "Additionally, the variability in TP63 mRNA expression across EBMD, SND, and pterygium IC samples suggests increased disease activity." (PMID 40094891, 2025). "TP63 mRNA expression was significantly lower in SND and pterygium samples than in controls (p = 0.042 and p = 0.006), but TP63 protein could not be detected by Western blot in any of the groups." (PMID 40094891, 2025).
sarcoma (2 papers, 2014 to 2019). A usually aggressive malignant neoplasm of the soft tissue or bone. "Among the genes that are downregulated in sarcoma in all three species, there are three known tumor suppressors: TP63, EPHA1, and DUSP26 (which may alternately function as an oncogene depending on the cancer context)." (PMID 30947707, 2019).
testicular cancer (2 papers, 2016 to 2017). A primary or metastatic malignant neoplasm that affects the testis. "Importantly, the TP63 (tumour protein p63) and TNFRSF10B (TNF receptor superfamily member 10b) genes are suppressed in primary human testicular cancer cells or cell lines, likely permitting tumour growth." (PMID 28893944, 2017). "However, treatment with inhibitors of histone deacetylases has been shown to reverse the epigenetic repression of the ERV9 LTR promoters, leading to induction of TP63 and TNFRSF10B transcription and ultimately promoting apoptosis of testicular cancer cells." (PMID 28893944, 2017).
thyroid cancer (2 papers, 2021 to 2022). "In another study, TAp63α, an isoform of the TP63 gene, was detected in thyroid cancer samples." (PMID 35626065, 2022).
vulvar carcinoma (2 papers, 2016 to 2021). "Hsa-miR-223 was also reported to work as a tumor-promotor in vulvar carcinoma by TP63 suppression." (PMID 34079579, 2021).
acute myeloid leukemia (1 paper, 2020). Acute myeloid leukemia (AML) is a group of neoplasms arising from precursor cells committed to the myeloid cell-line differentiation. "Expression of GAS5 was upregulated in patients with acute myeloid leukemia (AML) and the GAS5 rs55829688 CC genotype; the promoter activity of GAS5 was increased through interaction with TP63, which in turn led to a worse prognosis for AML." (PMID 32354045, 2020).
alopecia (1 paper, 2020). Hair loss usually from the scalp. "In humans, TP63 mutation causes several autosomal dominant ectodermal dysplasias, which are characterized by different combinations of limb, ectodermal, and orofacial abnormalities as well as alopecia, suggesting the role of p63 in maintaining stem cell proliferation." (PMID 32722415, 2020).
amblyopia (1 paper, 2021). Decreased vision that results from abnormal visual development. "In this series, several new findings were observed, including increased risk of amblyopia in most subtypes, as well as eyelid ptosis and lash ptosis in subtypes with TP63 or EDA1 gene variants." (PMID 33933124, 2021).
basal cell carcinoma (1 paper, 2025). A carcinoma involving the basal cells. "For CRSwNP, the shared impact on basal cell carcinoma of the TP63 variant appears to be more of an exception, as most CRSwNP loci with an impact on basaliomas had an opposite direction of effect." (PMID 41213931, 2025).
bladder disease (1 paper, 2025). "In summary, bioengineering urothelium with KRT5high TP63-expressing basal cells on a capsule vascular bed offers a promising strategy for bladder tissue engineering and provides a model for drug screening and bladder disease research." (PMID 40483513, 2025). "Moreover, the bioengineered urothelium from KRT5high TP63-expressing basal cells of normal or diseased human bladder would be a versatile and powerful tool for drug screening and the identification of novel therapeutic targets on different bladder diseases." (PMID 40483513, 2025).